GATA3 (GATA binding protein 3)
Diseases named in the same sentence as GATA3 in open-access papers (continued):
Sharing a sentence is not in itself a finding about the gene and the disease.
pleomorphic liposarcoma (1 paper, 2023). Pleomorphic liposarcoma (PLS), the rarest subtype of liposarcoma (LS), is an aggressive, fast growing tumor located usually in the deep soft tissues of the lower and upper extremities. "Our report may contribute for differential diagnosis of pleomorphic liposarcoma, epithelioid variant, with unexpected positive immunoreaction for GATA3." (PMID 37007224, 2023).
Pleuritis (1 paper, 2011). Inflammation of the pleura. "The number of toluidine blue+ cells, tryptase+ cells and GATA-3+ cells was significantly decreased in the parietal pleura of patients with tuberculous pleurisy compared with the control group of nonspecific pleuritis subjects." (PMID 21829471, 2011). "Elevated CD3, CD4, CCR4 and Th17 cells and decreased mast cells and GATA-3+ cells in the parietal pleura distinguish patients with untreated tuberculous pleurisy from those with nonspecific pleuritis." (PMID 21829471, 2011).
polyarticular JIA (1 paper, 2019). "GATA3 has been assessed as part of a deep whole genome sequencing study of children with polyarticular JIA." (PMID 31238969, 2019).
polyposis (1 paper, 2019). "We had also earlier reported that spontaneous polyposis in genetically susceptible APC deficient mice is marked by mixed TH2 and TH17 inflammation, and that MCs and GATA3 positive cells tend to accumulate together inside polyps." (PMID 31849960, 2019).
Psoriasiform dermatitis (1 paper, 2011). A skin abnormality characterized by redness and irritation, with thick, red skin that displays flaky, silver-white patches (scales). "Thus, GATA3 mRNA expression measured by RT-PCR was2.35-fold lower in the psoriasiform dermatitis lesions than in control mouseskin (p = 0.016, determined using theMann-Whitney U test)." (PMID 21611195, 2011).
pulmonary arterial hypertension (1 paper, 2014). Pulmonary arterial hypertension (PAH) is a group of diseases characterized by mean pulmonary artery pressure >20 mmHg and elevated pulmonary arterial resistance leading to right heart failure. "GATA3 gene expression is significantly lower in children with a combination of VSD and pulmonary arterial hypertension (PAH) than in those with PAH, so low GATA3 gene expression may be associated with VSD occurrence." (PMID 25165856, 2014).
RASopathy (1 paper, 2017). Developmental syndromes caused by germline mutations (or in rare cases by somatic mosaicism) in genes that alter the Ras subfamily and mitogen-activated protein kinases that control signal transduction. "In addition, two other noteworthy loci (one between KIRREL3 and ETS1, the other between GATA3 and CELF2) overlap between top results from ASD epistasis and RASopathy modifier mapping and contain genes of particular interest." (PMID 28076348, 2017).
relapsing-remitting multiple sclerosis (1 paper, 2024). The most common clinical variant of multiple sclerosis, characterized by recurrent acute exacerbations of neurologic dysfunction followed by partial or complete recovery. "Nevertheless, a bioinformatic analysis identified genetic variants of GATA3 as risk factors for augmenting the incidence of relapsing-remitting multiple sclerosis (RRMS)." (PMID 39768217, 2024).
Salmonella Infections (1 paper, 2013). Infections with bacteria of the genus SALMONELLA. "The CD1b- L-DCs did not express Notch ligands Jagged-1 and Delta-4 mRNA but constitutively expressed the transcription factor GATA-3 mRNA, whose production tended to fall after Salmonella infection (data not shown)." (PMID 24223964, 2013). "The CD1b- L-DCs constitutively expressed GATA-3, TNF-α, IL-23 and IL-4 genes which were down-regulated after Salmonella infection, but not after stimulation with helminth secretions." (PMID 24223964, 2013).
silicosis (1 paper, 2016). Silicosis is a respiratory disease caused by breathing in (inhaling) silica dust. "The levels of IL-4 and Th2 transcription factor GATA3 were suppressed especially in the late fibrosis stage, when the mice with developing silicosis already shifted the Th balance to favor Th2 predominance." (PMID 27354007, 2016).
Sleep disturbance (1 paper, 2024). An abnormal pattern in the quality, quantity, or characteristics of sleep. "GATA3 blood levels were depleted in PD patients who experienced sleep disturbances, suggesting that GATA3 could be potentially utilized as a novel non-invasive biomarker for early detection of PD, as well as predicting individuals who are at risk of developing non-motor symptoms." (PMID 39768217, 2024).
tubular carcinomas (1 paper, 2018). "Of the remaining tubular carcinomas, 3 fell in IntClust 7 (with 16q loss and MAP3K1 mutations), 4 fell in IntClust 8 (1q gain, 16q loss and PIK3CA and GATA3 mutations) and 6 belonged to IntClust 4 (few copy number alterations and activation of immune pathways)." (PMID 29532008, 2018).
ulcers (1 paper, 2014). "In particular, IL-33 was inversely correlated to the number of ulcers (r Spearman −0.638, p = 0.048) while T-bet, Gata-3 and IFN-γ were directly correlated with the number of ulcers (r Spearman 0.792, p = 0.011)." (PMID 24520333, 2014).
urothelial dysplasia (1 paper, 2022). A morphologic finding indicating the presence of dysplastic changes in the transitional cell epithelium of the urinary tract. "Vigilant search for surface urothelial dysplasia and detailed morphological analysis coupled with the use of GATA binding protein 3 (GATA-3), Prostate specific antigen (PSA) and NK3 homeobox-1 helps in arriving at the correct diagnosis." (PMID 36200017, 2022).
uterine tumors (1 paper, 2021). "In our study, GATA3 positive staining in an unselected sample of uterine tumors did not correspond well to any single histotype." (PMID 33986807, 2021).
vascular dementia (1 paper, 2024). A degenerative vascular disorder affecting the brain. "GATA3 has been highlighted in the regulatory signature of vascular dementia (VaD), raising the potential of targeting GATA3 for therapeutic interventions assignment as neurodegenerative conditions." (PMID 39768217, 2024).
vitiligo (1 paper, 2021). Generalized well circumscribed patches of leukoderma that are generally distributed over symmetric body locations and is due to autoimmune destruction of melanocytes. "It is hypothesized that skewed balance to Th1 is directly responsible for vitiligo development by changing IFN-γ/IL-4, Tbet/Gata3 profiles in vitiligo patients compared to controls." (PMID 33921371, 2021).
VKH syndrome (1 paper, 2015). "The frequencies of genotype and allele of 22 SNPs at TBX21, GATA3, Rorc genes didn't show a significant difference among BD patients, VKH syndrome patients and healthy controls." (PMID 25873156, 2015). "We applied the iPLEX system (Sequenom) and PCR-RFLP measurements to successfully evaluate 25 SNPs at TBX21, GATA3, Rorc and Foxp3 genes in an independent cohort containing 406 BD patients, 401 VKH syndrome patients and 613 healthy controls." (PMID 25873156, 2015). "The tested 25 SNPs in TBX21, GATA3, Rorc and Foxp3 did not associate with BD and VKH syndrome." (PMID 25873156, 2015).
Zinc deficiency (1 paper, 2020). A deficiency of the essential metal Zinc; an essential cofactor for many enzymes. "In conclusion, zinc deficiency aggravates inflammation by activating IRF/IL-23-mediated M1 macrophages and inhibiting GATA-3/IL-4 mediated M2 macrophages." (PMID 32331308, 2020).
tumor (722 papers, 2006 to 2026). "Low GATA3 mRNA levels are also associated with adverse tumor features, such as high histological grade, ER and PR negativity, and HER2 positivity (all p < 0.001; METABRIC cohorts)." (PMID 41024411, 2025). "Combined GATA3‐low (protein)/ER‐negative tumors were associated with increased tumor diameter, higher histologic grade, TNBC, and basal‐like (CK5/6 positive) phenotypes, compared to cases with GATA3 high (protein)/ER‐negative status (all p < 0.001)." (PMID 41024411, 2025). "Further, Lovastatin has been reported to reduce lipid accumulation and adipocyte differentiation in mice, in support of a potential effect on reducing tumor‐associated adipogenesis in GATA3‐low tumors." (PMID 41024411, 2025). "Here, we examined how GATA3‐low tumors are associated with features of immune responses and metabolic alterations, as well as basic tumor characteristics and clinical outcomes." (PMID 41024411, 2025). "Low GATA3 protein expression was strongly associated with tumor diameter >20 mm, high histologic grade, increased tumor cell proliferation (by Ki67), ER and PR negativity, and HER2 positivity (p ≤ 0.008)." (PMID 41024411, 2025). "Loss of GATA3 expression has been linked to increased tumor cell motility and invasion, emphasizing its role in tumor suppression." (PMID 40736702, 2025). "We find that low GATA3 expression associates with aggressive features like increased tumor diameter, higher histological grade, triple negative BC, and a basal‐like (CK5/6 positive) phenotype." (PMID 41024411, 2025). "The TGF‐βpathway genes (THBS1 and SMAD2) report on epithelial–mesenchymal transition and immunosuppressive signaling, while Th2‐associated markers (CCR4, GATA3) indicate a helper T‐cell polarization state that favors tumor progression." (PMID 41407509, 2025). "In contrast, silencing by DNA methylation of the GATA3 promoter only leads to increased tumour aggressiveness due to loss of GATA3 expression." (PMID 40585280, 2025). "Overall, the gene GATA3 is altered in 8.6% of tumour samples when both LOF mutations and CNA deletions are taken into account." (PMID 40585280, 2025). "G allele carriers exhibited both elevated GATA3 expression and an earlier age at diagnosis, implying a potential role in tumor initiation or progression." (PMID 40650155, 2025). "Both mechanisms of GATA3 inactivation were associated with similar molecular signatures linked to tumour progression, increased malignancy, and poorer prognosis." (PMID 40585280, 2025). "An increase in age, female sex, and increasing tumor size were associated with lower GATA3 levels (p<0.001, p<0.05, p<0.001, respectively)." (PMID 38668712, 2024). "Loss of Gata3 in transgenic mice stimulates mammary luminal tumor progression and overexpression of GATA3 suppresses epithelial-mesenchymal transition (EMT) in cancer cell lines." (PMID 38627785, 2024). "The findings that GATA3 stimulates DSB repair through HR and reconstitution of Gata3 restores the HR efficiency of Brca1-deficient cancer cells prompting us to investigate the response of Gata3-deficient tumor cells to PARP inhibitor." (PMID 38627785, 2024). "In contrast to the significant decrease in the number of Flag-expressing Brca1-deficient tumor cells, the number of Gata3-expressing Brca1-deficient tumor cells was insignificantly changed in response to OLA." (PMID 38627785, 2024). "Though OLA treatment of either Flag- or Gata3-expressing Brca1-deficient tumor cells resulted in significantly less colonies than DMSO treatment, the colonies formed by Gata3-expressing cells were significantly more than those formed by Flag-expressing cells." (PMID 38627785, 2024).
tumor (continued). "Tumor-associated macrophages (TAMs) of the M2 phenotype promote tumor progression, further implicating the role of GATA3 in tumor differentiation and aggressiveness." (PMID 39768217, 2024). "We further demonstrated that depletion of Gata3 sensitizes tumor cells to PARP inhibitor, and reconstitution of Gata3 enhances resistance of Brca1-deficient tumor cells to PARP inhibitor." (PMID 38627785, 2024). "Although several studies have reported the diagnostic and prognostic roles of GATA3 in malignant tumors, the results vary significantly according to tumor type." (PMID 37629741, 2023). "We also demonstrated that FRA1 is required for the activation of EMT during GATA3 deficient tumor initiation and metastasis." (PMID 37353480, 2023). "Overexpression of GATA3 suppresses EMT in cancer cell lines and loss of Gata3 in oncogene transgenic mice stimulates mammary luminal tumor progression with expansion of stem cell-like tumor cells." (PMID 37353480, 2023). "Reconstitution of Gata3 in Gata3 deficient tumor cells restores c-Fos expression inhibiting EMT and tumorigenesis." (PMID 37353480, 2023). "GATA3 released from tumor-associated macrophage-derived exosomes contributes to tumor growth in the tumor microenvironment of high-grade serous ovarian carcinoma." (PMID 38107591, 2023). "This suggests that in GATA3-deficient tumor cells, the acquisition of mesenchymal traits by the activation of Fra1 is dominant over the loss of epithelial features by the deficiency of c-Fos, in activating EMT and driving CSC function." (PMID 37353480, 2023). "In concordance with previous studies, they also found, in this cohort, that a higher GATA3+/Tbet+ ratio after BCG induction was significantly associated with tumor recurrence and progression." (PMID 38067259, 2023). "We explored the associations between the tumor subtypes and GATA3 expression, and our results revealed that BLCA with high GATA3 expression was more inclined to be luminal subtype." (PMID 35647011, 2022). "Our results expand the spectrum of SATB2 and GATA3-positive neoplasms, with relevant practical diagnostic correlates, and suggest that Hyams’ grade 4 ONBs are not only clinically but also biologically different from lower grade ONBs." (PMID 35522392, 2022). "We confirmed that after long term culture (at least 6 months), tumor cells derived from cells with high levels of Gata3 maintained their expression of Gata3 and E-Cad (encoded by Cdh1) (and data not shown)." (PMID 34976209, 2022). "In cases where CK 5/6 expression was less than ++, including either central loss of staining or complete loss of staining, then any GATA3 staining pattern was indicative of a luminal tumor." (PMID 36230835, 2022). "A significant reduction in tumor size was appreciated, and loss of GATA-3 itself, and 2 out of 3 target genes examined, was observed." (PMID 36329027, 2022). "Consistently, our findings showed a positive correlation between GATA3 and E-cadherin, a tumor suppressor associated with cell to cell adhesion which is an important event that contributes to tumor inhibition." (PMID 35804829, 2022). "GATA3 participates in driving tumor growth and metastasis and is thus closely associated with SKCM survival." (PMID 36438905, 2022). "Spatial heterogeneity was identified in all five BBCs, with almost all heterogeneous mutations between bilateral tumor lesion (range: 95.4–100%), except for only one ubiquitous mutation GATA3 in patient P03." (PMID 36249030, 2022). "K14-Cre Brca1f/f p53f/f TslprKO tumor suppression in the test group was associated with the infiltration of GATA3+ Th2 cells in the tumors." (PMID 35657353, 2022). "IL-9 mRNA levels in tumours showed a marked correlation with the Th9-associated transcription factors Irf4, Gata3, and Spi1, as well as with Socs3." (PMID 35793807, 2022).
tumor (continued). "To genetically confirm the role of Brca1 in regulating the methylation of Gata3 gene we treated p18-/- (Brca1 proficient) and p18-/-;Brca1MGKO (Brca1 deficient) tumor cells with DAC." (PMID 34373738, 2021). "The down expression of GATA3 in BC is linked to a tumor phenotype that is prone to invasive growth and has a poor prognosis." (PMID 34126989, 2021). "We demonstrated that reconstitution of Gata3 in Brca1-deficient tumor cells activates MET and eliminates potential for tumor initiation and metastasis." (PMID 34373738, 2021). "Here again, we confirmed that the ileal mRNAs encoding Gata3, Bcl6, Rorc, and Tbx21 were increased in tumor bearers at day 10 of implantation compared to naive counterparts." (PMID 33262469, 2021). "Reconstitution of Gata3 in Brca1-deficient tumor cells activated mesenchymal-epithelial transition, suppressing tumor initiation and metastasis." (PMID 34373738, 2021). "In fact, higher positivity for each protein was identified in different groups of tumours with GATA3 positive expression associated with well differentiated tumours and ERα with loss of urothelial differentiation." (PMID 34690921, 2021). "Similar to the results of this meta-analysis, four studies reported significant association between GATA3 expression and low grade and low stage tumours." (PMID 34690921, 2021). "On the contrary, ERα-positivity was associated to higher grade tumours; while ERα and ERβ were inversely correlated with GATA3 expression." (PMID 34690921, 2021). "In urothelial cell line models, the loss of GATA3 expression promoted tumor cell migration and invasion via upregulation of oncogenes." (PMID 34707176, 2021). "GATA3 mutations can lead to active forms of the GATA3 protein that contribute to tumor growth in BC cell xenografts and promote precocious lobuloalveolar development in transgenic mice." (PMID 34831189, 2021). "p18;Gata3 double mutant mice provide us a genetic model and a unique opportunity to dissect the role of Gata3 loss in the regulation of tumor cell differentiation in vivo." (PMID 34373738, 2021). "A logical interpretation is that sequential mutation of GATA3 facilitates acquisition of invasive characteristics following PIK3CA mutations to promote tumor initiation." (PMID 33795819, 2021). "We previously showed that GATA3 is progressively lost in the prostate epithelium of Pten-deficient mice, while enforced GATA3 expression slows down tumor progression." (PMID 32894216, 2020). "We raised a polyclonal antiserum against the novel 44aa peptide, which specifically recognized a shorter GATA3 protein of the expected size (37 kDa) exclusively in a tumor carrying the mutation and in cells transduced with the mutant cDNA." (PMID 32587399, 2020). "Accordingly, compared with WT counterparts, KO derived tumor infiltrating Treg cells upregulated the expression level of Gata3, which encodes the master transcriptional factor (TF) of Th2, as well as Th2 related cytokine IL4." (PMID 32477338, 2020). "Ectopic overexpression of GATA-3 was shown to lead to reduced tumor outgrowth in the mammary fat pad and loss of metastatic potential of aggressive human tumor cell lines." (PMID 30041613, 2018). "In this light, our data suggest that YAP1 and GATA3 are important target genes for future analysis on the impact of SMYD3‐mediated regulation of tumor‐associated genes." (PMID 28781952, 2017). "Recently, we confirmed a Th2 predisposition (GATA3>T-bet) of tumor-infiltrating immune cells in high-risk NMIBC patients with response to BCG." (PMID 28005163, 2017). "Because results from clinical samples showed that GATA3 expression was associated with tumour invasiveness, we next investigated the effects of GATA3 on cell migration and invasion by transwell migration and Matrigel invasion assays, respectively." (PMID 28263977, 2017).